TNF (tumor necrosis factor)
Diseases named in the same sentence as TNF in open-access papers (continued):
Sharing a sentence is not in itself a finding about the gene and the disease.
tuberculosis (continued). "We, therefore, characterised and compared the expression of IL-6, TNF-α, IFN-γ, and IL-10 in whole blood of treatment naïve TB patients stimulated with heat-killed Mycobacterium tuberculosis stratified by HIV status and the level of CD4 count." (PMID 35025927, 2022). "IFN-γ and TNF-α value of presumptive for tuberculosis cases were not statistically significant." (PMID 35198736, 2022). "Taken together, our study uncovered a previously unknown role of FBXW7 in regulating TNF-α dynamics during mycobacterial infection, which provides new insights into understanding the role of FBXW7 in anti-tuberculosis immunity and its related clinical significance." (PMID 35651754, 2022). "This study aimed to explore the contribution of tumor necrosis factor (TNF) in the recruitment of B-cell and secretion of immunoglobulins (Igs) during cerebral tuberculosis (TB)." (PMID 32742607, 2020). "Clinicians should be aware of the risk of paradoxical reactions/immune reconstitution inflammatory syndrome when treating patients with tuberculosis of the central nervous system and should consider the prompt anti-TNF-α agents in cases not responding to corticosteroids." (PMID 33120751, 2020). "Furthermore, there was a report on switching of systemic Th1 to tissue-resident Th17 protective response upon mucosal administration of adjuvanted tuberculosis vaccine in mice and this protection was independent of TNFα and IL-17 receptors." (PMID 33391267, 2020). "Next, we examined the implication of nNOS in the pathogenesis of CNS TB, brain tissues of intracranially M. tuberculosis infected TNFf/f, BTNF-/-, and TNF-/- mice were used for nNOS mRNA expression." (PMID 32742607, 2020). "Patients exposed to both TNF-α and non-TNF-α biologic therapies may have a higher incidence of tuberculosis disease compared to the background risk of 681 cases per 100,000 per year in the Western Cape." (PMID 33256634, 2020). "We evaluated macrophage expression of VDR, TLR2, cathelicidin, and TNF-α, and production of IL-1β in HIV-seronegative persons with previous EPTB, previous pulmonary TB, latent M. tuberculosis infection, and uninfected TB contacts." (PMID 31039752, 2019). "We analyzed frequencies of antigen-specific CD4 and CD8 T cells expressing IFNγ, IL-2, TNF and/or IL-17 from adolescents or adults, with or without Mycobacterium tuberculosis (M. tb) infection, who received MVA85A, AERAS-402, H1:IC31, H56:IC31, M72/AS01E, ID93+GLA-SE or BCG." (PMID 30830940, 2019). "Interestingly, a review of the therapeutic agents for Crohn’s inflammation suggested that previously prescribed anti-inflammatory agents were actually treating MAP, while the strong contemporary anti-inflammatory TNF inhibitors are permissive for both MAP and tuberculosis." (PMID 31627347, 2019). "Moreover, in the clinical course of human TB, high levels of TNF-α have been associated with clinical decline in patients with TB, and higher secretion of TNF-α in humans could be associated with the haematogenous dissemination of M. tuberculosis to other organs." (PMID 29298876, 2018). "Besides, none developed active tuberculosis within 1 year after TNF inhibitor initiation among patients who received QFT-GIT-alone." (PMID 29975703, 2018). "Studies have shown that M. tuberculosis in MDR patients results in comparatively strong immune responses, resulting in a significant increase in TNF-α and IFN-γ levels in peripheral blood, which play an important role in the pathogenesis of TB." (PMID 28910318, 2017). "Additionally, even with concomitant use of TNF blockers, none of the subjects developed tuberculosis in the study." (PMID 28886099, 2017). "We previously demonstrated that the TNF-α–only TEFF signature distinguished tuberculosis from LTBI with high sensitivity and specificity, with the proportion of these cells being significantly higher in patients with tuberculosis than in patients with LTBI, including patients with HIV coinfection." (PMID 28329119, 2017).
tuberculosis (continued). "Furthermore, the outcomes were not different in patients who resumed TNF inhibitors before completion of anti-tuberculosis treatment or after completion." (PMID 27101309, 2016). "In our study using a nationwide registry in an area with intermediate tuberculosis burden, 23 patients restarted TNF inhibitors after initiating anti-tuberculosis treatment without aggravation of the tuberculosis, delay of the treatment or tuberculosis-related deaths." (PMID 27101309, 2016). "Tumor necrosis factor alpha (TNF-α) plays important and contradictory roles in the pathogenesis of many infectious diseases, including tuberculosis (TB)." (PMID 25999670, 2015). "We compared two interferon gamma release assays (IGRAs), QuantiFERON-TB Gold In-Tube (QFT-GIT) and T-SPOT.TB, for diagnosis of latent tuberculosis infection (LTBI) in patients before and while receiving tumor necrosis factor (TNF)-α antagonist therapy." (PMID 26474294, 2015). "In summary, we found that M. tuberculosis-specific antigens induced production of IL-21 in addition to IFN-γ, TNF-α, IL-2 and IL-17 by NKT cells in pleural fluids from TB patients." (PMID 26416419, 2015). "However, as MTB-infected monocytes or macrophages are proposed to be the major source of TNF-α and MMP-9 in tuberculosis, and there is emerging evidence that cell-cell interaction between immune cells and stromal cells are implicated the intercellular network to drive MMP production in tuberculosis." (PMID 26367274, 2015). "In the present study, we found that after stimulation with M. tuberculosis antigens, NKT cells isolated from tuberculosis (TB) pleural fluid mononuclear cells (PFMCs) produced IL-21 and other cytokines including IFN-γ, TNF-α, IL-2 and IL-17." (PMID 26416419, 2015). "Additionally, C1qC protein level in pleural effusion shows improved power in discriminating tuberculosis from non-tuberculosis pleurisy when compared to other inflammatory markers, such as IL-6 and TNF-α." (PMID 24647646, 2014). "Spouses with positive IFN-γ responses to M. tuberculosis ESAT-6 (>62.5 pg/mL) and TB patients showed high production of IL-17, CXCL10 and TNF-α." (PMID 24260295, 2013). "Measurement of the proportion of TNF-α-only secreting M. tuberculosis-responsive CD4+ cells has proved promising to distinguish between active tuberculosis and latent tuberculosis infection but neither earlier data nor our findings have clinically sufficient discriminatory power." (PMID 23966657, 2013). "Furthermore, our results show that Tm-TNF contributes to the initial containment of re-emerging tuberculosis but is not sufficient for long-term mycobacteria containment resembling the outcome of chronic infection." (PMID 22132068, 2011). "Leucocyte activating chemokines such as CCL2, CCL3, and CXCL8 together with proinflammatory IFNγ, TNFα and downmodulatory IL10 play a central role in the restriction of M. tuberculosis infections, but is unclear whether these markers are indicative of tuberculosis disease severity." (PMID 20041183, 2009). "In addition, we did not observe any differences in BCG-induced TNFα between controls and tuberculosis patients, P > 0.05 at either time interval studied." (PMID 16001981, 2005). "Infections such as tuberculosis (TB), hepatitis B virus (HBV), and hepatitis C virus (HCV) may occur as adverse effects of TNF-α inhibitor therapies." (PMID 40711067, 2025). "The most important concern with biologics is reactivation of tuberculosis (TB), which is primarily observed with anti-TNF agents than non-TNF biologics." (PMID 40376361, 2025). "Assuring the patient does not have latent tuberculosis (TB) is a necessary extra step while using TNF-a inhibitors like adalimumab." (PMID 39390211, 2024). "Both the synthesis of TNF-α and the virulence of M. tuberculosis in human monocytes, as well as the rise in serum TNF-α levels and the worsening of a patient's clinical condition in cases of severe TB, are related." (PMID 37007342, 2023).
tuberculosis (continued). "Interestingly, this study discovered that the levels of TNF-a and IL-6 in sputum were not significantly different between active tuberculosis patients and controls, indicating that dysregulation of cytokines occurs mostly in the circulation, rather than the lungs." (PMID 35457250, 2022). "TNF-α response to M. tuberculosis antigens may be elevated and IFN-γ response depressed at the time of TB diagnosis, with a later decline in TNF-α and elevation of IFN-γ associated with successful resolution of disease." (PMID 32736606, 2020). "Tuberculosis-related IRIS (TB-IRIS) upon tumor necrosis factor (TNF)-α inhibitor treatment has been reported in non-human immunodeficiency virus (HIV) patients." (PMID 31905985, 2019). "Tuberculosis may be an exception to this rule, as the majority of reported cases from the literature and our experience were receiving neither corticosteroids nor TNF-a inhibitors when their reactivation was documented." (PMID 31484550, 2019). "These observational studies have not detected any relapse of tuberculosis after TNF inhibitors recommencement in patients who had experienced TNF inhibitor-related tuberculosis and therefore, TNF inhibitors could be resumed in tuberculosis patients after appropriate anti-tuberculosis treatment." (PMID 27101309, 2016). "On the other hand, anti-TNF-α therapy has demonstrated an anecdotal prompt and beneficial effect in controlling steroid-resistant tuberculosis paradoxical reactions that occur after initiating antituberculosis treatment for severe tuberculosis with or without prior exposure to anti-TNF-α therapy." (PMID 26273486, 2015). "Therefore, patients eligible for anti-TNF-α therapy require careful evaluation and need to be investigated about possible previous exposure to MTB, as its use may expose patients to an increased risk of developing active TB and reactivation of latent tuberculosis infection (LTBI)." (PMID 24554385, 2014). "Our data showed that mycobacterium tuberculosis (Mtb)-specific IFN-γ, TNF-α, IL-2, IL-6, IL-10, IL-5, IP-10, IL-1Ra, CXCL-1 and MCP-1 responses based on QFT-Plus significantly differed between Mtb-infected (including ATB, LTBI and previous TB) and uninfected healthy populations." (PMID 38166667, 2024). "It was not difficult to find that IL-17, TNF, AGE-RAGE signaling pathway, Tuberculosis, Hepatitis B, and Toxoplasmosis were key pathways." (PMID 37078344, 2024). "Additionally, patients with HTLV-1-associated myelopathy and tuberculosis exhibit higher TNF/IL-10 and IFN-γ/IL-10 ratios compared to those without TB." (PMID 39772183, 2024). "Recent data from mice and non-human primate models of tuberculosis suggested that CD153, a TNF super family member, plays an important role in Mycobacterium tuberculosis (Mtb) control." (PMID 32678272, 2021). "It was therefore concluded that TNF was indispensable to generate protective immunity against M. tuberculosis infection of the central nervous system and unequivocally established the non-redundancy of TNF as a critical mediator of immune protection against CNS-TB." (PMID 26112704, 2015). "CXCL10 and TNF-α may be used as adjunct markers alongside an IFN-γ release assay to diagnose M. tuberculosis infection, and IL-17 and IL-10 production may differentiate individuals with LTBI from active TB." (PMID 24260295, 2013). "The mean IFN-γ level in the positive-control well increased significantly (P < 0.001) after treatment with TNF-α antagonists, whereas the IFN-γ level in the tuberculosis-antigen well did not change." (PMID 22709461, 2012). "Since pathology in TB typically involves inflammatory aggregates around infected cells, where TNF-α plays an important role, we predicted that IL-4 would inhibit the ability of cells to remove M. tuberculosis by apoptosis of infected cells, through the extrinsic pathway, which is activated by TNF-α." (PMID 21253484, 2011).
tuberculosis (continued). "Our conclusion was that monocytes from TB patients—but not monocytes from those infected with M. tuberculosis but asymptomatic, such as individuals with latent TB—were likely less responsive to extrinsic stimuli promoting apoptosis such as TNF-α." (PMID 21253484, 2011). "Tsaoet al. studied bronchoalveolar lavage (BAL) fluid and serum TNF-α, IL1β, and TNF-α receptor levelsin patients with cavitated and noncavitated tuberculosis." (PMID 17497033, 2007). "Tuberculosis does not seem to be a prevalent problem in our population, but severe evolution in the cases reported to date makes LTBI screening mandatory prior to anti-TNFα drug implementation." (PMID 26635208, 2015). "In cultures without stimulus, the median TNF-α level among the group with HTLV-1 infection and tuberculosis (368 pg/mL) ranging from 128 to 5527 pg/mL was higher (p = 0.004) than that observed in patients with only tuberculosis (73 pg/mL), which ranged from 0 to 738 pg/mL." (PMID 22925731, 2012). "Conversely, M. tuberculosis-specific stimulation of IFN-γ (but not TNF-α) and IFN-γR signaling are significantly depressed in active TB, which correlates with TB disease severity and activity." (PMID 26495323, 2015). "Since Mycobacterium tuberculosis is no longer present in the post-TB airflow obstruction patients, there is no real inducing element of TNF-α, which could justify its low concentration in COPD/post-TB patients." (PMID 32998687, 2020).
ulcerative colitis (715 papers, 2008 to 2026). An inflammatory bowel disease involving the mucosal surface of the large intestine and rectum. "Neutrophils also secrete pro-inflammatory cytokines (TNF-α, IL-1β) and chemokines (IL-8—a potent chemotactic factor for neutrophils, whose concentration has been associated with ulcerative colitis endoscopic and histological activity)." (PMID 41010030, 2025). "It is important to highlight that while this study has identified targets associated with ulcerative colitis (UC), such as TNF, ESR1, and HSP90AA1, the fundamental pathology of UC is driven by more specific factors and biomarkers." (PMID 40895135, 2025). "This study aimed to uncover biomarkers associated with fibroblasts to diagnose ulcerative colitis (UC) and predict sensitivity to TNFα inhibitors." (PMID 39428941, 2025). "The occurrence of HV during a period of ulcerative colitis inactivity strongly suggests a causal relationship with anti-TNF treatment." (PMID 39861147, 2025). "Although immunosuppressive therapy with anti-TNF-α and thiopurine in patients with ulcerative colitis has been associated with a two-to-threefold increase in lymphoma incidence, others have reported no such increase." (PMID 40969788, 2025). "Although the mechanism that causes ulcerative colitis is still not fully known, it is accepted that TNF-α and oxidative stress triggered by them play a part in the onset and progression of the disease in a complex interaction." (PMID 40428786, 2025). "Subsequently, infliximab, a tumor necrosis factor-alpha (TNFα) inhibitor, was administered, which achieved remission of the ulcerative colitis and improved the pain associated with the disease." (PMID 39596554, 2024). "Among the inflammatory cytokines associated with ulcerative colitis (UC), TNF-α plays a pivotal role in initiating the inflammatory response, which manifests during the early stages of inflammation." (PMID 38346819, 2024). "TNF-α promotes the migration and invasiveness of colorectal cancer and participates in colorectal carcinogenesis associated with ulcerative colitis." (PMID 37569878, 2023). "Some inflammatory cytokines associated with ulcerative colitis include tumor necrosis factor alpha (TNF-α) and interleukin-1 beta (IL-1β)." (PMID 38024826, 2023). "Inflammatory macrophages replace resident macrophages and cause a spatial shift of TNF production during ulcerative colitis via a cytokine production network formed with T and B cells." (PMID 37344477, 2023). "While anti-TNF can be used for severe ulcerative colitis treatment, there’s a risk of recurrence if it is discontinued." (PMID 37904100, 2023). "Ulcerative colitis is caused by the uncontrolled actions of nuclear factor kappa B (NF-κB) signaling pathway and proinflammatory cytokines such as TNF-α, and IL-1β, causing intestinal tissue damage." (PMID 36457188, 2023). "Serum inflammatory markers such as TNF-α, IL-6 and IL-1β are often considered as hallmark of ulcerative colitis." (PMID 36159798, 2022). "In an ulcerative colitis (UC)-associated mouse model, β-carotene supplementation at 20 mg/kg body weight (BW)/day for 28 days significantly reduced colonic IL-6 and TNF-α levels, which was in line with our findings." (PMID 34646849, 2021). "The increased TNF-α in ulcerative colitis patients has been associated with decreased microbial production of GABA, indicating a role for gut microbiota-derived GABA in TNF-α-mediated inflammations." (PMID 33066564, 2020). "Recent studies have reported expansion of a colonic mesenchymal subset in adult ulcerative colitis and associated this with resistance to anti-TNF treatment." (PMID 33290721, 2020). "TNF-α also appears to play a significant role in the inflammatory process associated with ulcerative colitis." (PMID 30971953, 2019).